TTLL5 (tubulin tyrosine ligase like 5)
Description:
Polyglutamylase which modifies tubulin, generating polyglutamate side chains on the gamma-carboxyl group of specific glutamate residues within the C-terminal tail of tubulin. Preferentially mediates ATP-dependent initiation step of the polyglutamylation reaction over the elongation step. Preferentially modifies the alpha-tubulin tail over a beta-tail (By similarity). Required for CCSAP localization to both polyglutamylated spindle and cilia microtubules. Increases the effects of transcriptional coactivator NCOA2/TIF2 in glucocorticoid receptor-mediated repression and induction and in androgen receptor-mediated induction.
Synonyms: KIAA0998; STAMP; CORD19
Tractability: Antibody: its Gene Ontology location is reachable by antibodies, with high confidence. PROTAC: ubiquitination databases record sites on it.
Gene: Protein-coding gene on chromosome 14 (75,633,625 to 75,955,084, forward strand). Ensembl gene ENSG00000119685.
Subcellular location: Cell projection, cilium; Cytoplasm, cytoskeleton, cilium basal body; Nucleus; Cytoplasm
Subcellular location (Human Protein Atlas): Cytosol; Plasma membrane
Pathways (Reactome):
Metabolism of proteins: Carboxyterminal post-translational modifications of tubulin
Gene Ontology:
Molecular function: protein-glutamic acid ligase activity, elongating; protein-glutamic acid ligase activity, initiating; tubulin binding; tubulin-glutamic acid ligase activity
Biological process: retina development in camera-type eye; protein polyglutamylation; sperm axoneme assembly
Cellular component: centrosome; cytoplasm; cytosol; nucleus; ciliary basal body; cilium
Genetic constraint (gnomAD): Loss-of-function variants: 119 observed, 156.04 expected, observed/expected ratio (o/e) 0.76, 90% interval 0.66 to 0.89. The upper end of that interval is the gene's LOEUF score, 0.89, which puts it in group 3 of 6, group 1 being the genes least tolerant of losing a copy. Missense variants: 1,478 observed, 1,576.4 expected, observed/expected ratio (o/e) 0.94, 90% interval 0.9 to 0.98. Synonymous variants: 516 observed, 564.66 expected, observed/expected ratio (o/e) 0.91, 90% interval 0.85 to 0.98.
Homologues: Orthologues: chimpanzee TTLL5 (98% identical), macaque TTLL5 (97% identical), dog TTLL5 (93% identical), rabbit TTLL5 (89% identical), pig TTLL5 (86% identical).
Diseases named in the same sentence as TTLL5 in open-access papers:
TTLL5 is named in the same sentence as 26 diseases in open-access papers, as found by Europe PMC text mining. Sharing a sentence is not in itself a finding about the gene and the disease. The quoted sentences say what the papers report.
Retinal dystrophy (7 papers, 2021 to 2023). Retinal dystrophy is an abnormality of the retina associated with a hereditary process. "RPGRORF15 glutamylation is regulated by the tubulin-tyrosine ligase-like 5 (TTLL5) enzyme, which has also been associated with retinal dystrophies." (PMID 36835250, 2023). "Post-translational glutamylation of the photoreceptor-specific RPGRORF15 isoform by the TTLL5 enzyme is essential for its optimal function in photoreceptors, and loss of TTLL5 leads to retinal dystrophy with a cone phenotype." (PMID 36445968, 2022). "To date, nineteen cases of TTLL5-associated retinal dystrophy have been reported across sixteen different families." (PMID 35365235, 2022). "The truncating variants, which express almost full-length RPGRORF15protein, also impair RPGRORF15 glutamylation, mirroring the cone phenotype associated with the loss-of-function TTLL5-related retinal dystrophy." (PMID 36445968, 2022). "Specifically, both studies report biallelic variants in TTLL5 causing cone (n = 5) or cone–rod (n = 4) phenotypes and one case of early onset severe retinal dystrophy." (PMID 36445968, 2022). "Variants of the TTLL5 gene are a rare cause of retinal dystrophy and to date only a handful of cases have been described in the literature, with two studies in particular, detailing clinical and genetic findings." (PMID 36445968, 2022). "TTLL5 mutations should be considered in the differential diagnoses for sectoral retinal dystrophies and mild COD." (PMID 35365235, 2022). "Shortly after the characterization of CEP41 as a Joubert syndrome protein, homozygous mutations in TTLL5 were reported to cause retinal dystrophy in a subset of patient families with inherited retinal degenerations." (PMID 33748109, 2021). "Following that the loss of the TTLL5 enzyme leads to a cone-dominated phenotype, where full-length RPGR would not be glutamylated, we hypothesize that the phenotype of the distal pathogenic RPGR variants would merge with the TTLL5 retinal dystrophy." (PMID 36445968, 2022). "Furthermore, a specific isoform of RPGR is a substrate for TTLL5 and mutations in TTLL5 cause retinal dystrophy in humans and slow photoreceptor degeneration in mice leading to the proposal that glutamylation of RPGR is required for its normal function." (PMID 35404950, 2022). "Interestingly, in mice, the RPGRORF15 (the photoreceptor-specific ORF15 variant of retinitis pigmentosa GTPase regulator) implicated in retinal dystrophy actually localizes to connecting cilia of photoreceptors and is glutamylated by TTLL5 in vivo." (PMID 33748109, 2021). "Here, we report a complete clinical description of five French patients presenting either COD/CORD or early-onset severe retinal dystrophy (EOSRD) linked to six novel pathogenic biallelic variants, among which two are large intragenic deletions in TTLL5." (PMID 34203883, 2021). "The tubulin tyrosine ligase like-5 (TTLL5) glutamylates RPGRORF15 in its Glu-Gly–rich repetitive region, which contains motifs homologous to the α-tubulin C-terminal tail; loss of glutamylation has pathological consequences in developing retinal dystrophy." (PMID 38069202, 2023). "The age of onset among these three patients was variable, as were presenting symptoms, suggesting that TTLL5-mediated retinal dystrophy may be more phenotypically varied than previously reported." (PMID 35365235, 2022).
retinal degeneration (6 papers, 2016 to 2026). Degeneration of the retina. "RPGR function requires glutamylation by tubulin tyrosine ligase-like 5 (TTLL5) whose mutation is also linked to severe forms of retinal degeneration." (PMID 41941273, 2026). "Failed glutamylation of RPGRORF15 may impair photoreceptor function and explain the retinal degeneration caused by mutations in TTLL5." (PMID 35365235, 2022). "Therefore, reducing initiating glutamylases such as TTLL5, which has also been associated with hyperglutamylation and retinal degeneration, could restore the balance of glutamylation in AGBL5 deficient cells." (PMID 40926193, 2025). "In this study, the phenotype of TTLL5-related retinal degeneration is expanded to include mild COD and sectoral CORD, and structural modeling was performed to elucidate potential mechanisms of disease pathogenesis." (PMID 35365235, 2022). "Recently, a member of the TTLL family, TTLL5, was reported to be involved in human retinal degeneration." (PMID 26941104, 2016). "Further characterization of patients with TTLL5-related retinal degeneration is required and will ultimately be beneficial in the future treatment of this condition, both in understanding the natural history of disease progression and identifying suitable outcome measurements for therapy." (PMID 35365235, 2022). "Middle-age onset and slow progression of retinal degeneration in most patients, combined with the availability of a murine model reproducing the human phenotype and the relatively suitable size of the gene, make TTLL5 a good target for gene therapy approaches." (PMID 34203883, 2021). "TTLL5 pathogenic mutations even lead to the absence of glutamylation on RPGR, compromising its function and leading to a retinal degeneration phenotype." (PMID 35656327, 2022).
cone-rod dystrophy (5 papers, 2021 to 2025). Inherited retinal dystrophies that belong to the group of pigmentary retinopathies. "Recently, cone/cone-rod dystrophy was also described in patients harbouring mutations in TTLL5 (tubulin tyrosine ligase like-5) and ARL3 (Arf-like protein 3), both interacting partners of RPGR." (PMID 33805381, 2021). "Variants of the TTLL5 gene, which encodes tubulin tyrosine ligase-like family member five, are a rare cause of cone dystrophy (COD) or cone-rod dystrophy (CORD)." (PMID 34203883, 2021). "Although mutations in TTLL5 cause cone-rod dystrophy in humans and reduced male fertility we hypothesized that on an AGBL5 knockout background, reduction in TTLL5 levels could be potentially therapeutic." (PMID 40926193, 2025). "CDHR1, TTLL5, PRPF6, and IFT140 have been reported to play roles in human disorders of cone-rod dystrophy and cone dystrophy or retinitis pigmentosa." (PMID 35456484, 2022).
cone dystrophy (4 papers, 2021 to 2022). An inherited ocular disorder characterized by the loss of cone cells, the photoreceptors responsible for both central and color vision. "In humans, TTLL5 mutations were first characterized as a cause of cone–rod dystrophy (CORD) or cone dystrophy (COD) and the protein was localized to the ciliary body of photoreceptors." (PMID 35365235, 2022). "Since the CID of TTLL5 binds the C-terminal basic domain of RPGRORF15 to glutamylate the protein, we analyzed how variants associated with a predominant cone phenotype (cone–rod, mixed cone–cone–rod, or cone dystrophy) located in the distal end of RPGRORF15 affect this interaction." (PMID 36445968, 2022).
retinal disease (4 papers, 2021 to 2025). "Mutations of TTLL5 have been linked to retinal disease in humans and a Ttll5 mutant mouse is reported to undergo late (~20 months-old) photoreceptor degeneration." (PMID 35404950, 2022). "It has been suggested that truncating mutations in TTLL5 may cause syndromic disease with azoospermia in addition to retinal disease, while missense mutations lead to isolated retinal findings." (PMID 35365235, 2022). "Due to the rarity of the disorder, international collaborative studies would be necessary to define the full spectrum of TTLL5-related retinal disease and genotype-phenotype correlations." (PMID 34203883, 2021). "Due to the advances in use of antisense oligonucleotides (ASOs) in treatment of rare disease, including rare retinal diseases, we were interested to test whether an siRNA approach to reducing TTLL5 levels could rescue the ciliogenesis and glutamylation defects observed in AGBL5−/− clones." (PMID 40926193, 2025).
retinitis pigmentosa (3 papers, 2021 to 2022). Retinitis pigmentosa (RP) is an inherited retinal dystrophy leading to progressive loss of the photoreceptors and retinal pigment epithelium and resulting in blindness usually after several decades. "However, some rare cases of retinitis pigmentosa (RP) presumably linked with TTLL5 have been reported in the literature." (PMID 34203883, 2021).
Azoospermia (1 paper, 2022). Absence of any measurable level of sperm,whereby spermatozoa cannot be observed even after centrifugation of the semen pellet. "A patient with TTLL5 mutations has been reported with azoospermia, similar to mice with TTLL5-deficiency." (PMID 35365235, 2022).
ciliopathies (1 paper, 2025). "However, it is not clear why defects in TTLL5, which mainly localizes to centrosomes, lead to symptoms of ciliopathies." (PMID 40229407, 2025).
Infertility (1 paper, 2025). "Mutation of the glutamylase TTLL5 causes cone photoreceptor dystrophy and infertility, likely owing to deficiencies of cilia and flagella." (PMID 40229407, 2025).
leukemia (1 paper, 2025). A malignant (clonal) hematologic disorder, involving hematopoietic stem cells and characterized by the presence of primitive or atypical myeloid or lymphoid cells in the bone marrow and the blood. "Besides lymphoma- and/or leukemia-related genes, the most frequently mutated tumor suppressor genes included AFAP1L1, FBN3, MTSS2, and TTLL5, with each being mutated in at least 10% of cHL cases." (PMID 41296384, 2025).
tumor (2 papers, 2010 to 2024). "Furthermore, we found that gene TTLL5 and CLEC12A have a higher expression on the interactive zone between domains 1 and 5, which may infer their potential relationship with the tumor-immune interaction." (PMID 38844966, 2024).
neurodegenerative disease (1 paper, 2023). A disorder of the central nervous system characterized by gradual and progressive loss of neural tissue and neurologic function. "That TTLL5 is not essential for survival also makes this protein an interesting candidate drug target to modulate its glutamylation activity to regulate and possibly even increase MT transport in neurodegenerative diseases where MT transport is known to be affected." (PMID 37345829, 2023).
TTLL5 also shares sentences with these, for which no sentence is quoted: periodontitis (3 papers); osteoporosis (2); Blindness (1); breast carcinoma (1); cancer (1); chronic myeloid leukemia (1); infection (1); Joubert syndrome (1); kidney cancer (1); lymphoma (1); ovarian carcinoma (1); prostate carcinoma (1); scoliosis (1); silicosis (1).